PIK3C2A (phosphatidylinositol-4-phosphate 3-kinase catalytic subunit type 2 alpha)
Description:
Generates phosphatidylinositol 3-phosphate (PtdIns3P) and phosphatidylinositol 3,4-bisphosphate (PtdIns(3,4)P2) that act as second messengers. Has a role in several intracellular trafficking events. Functions in insulin signaling and secretion. Required for translocation of the glucose transporter SLC2A4/GLUT4 to the plasma membrane and glucose uptake in response to insulin-mediated RHOQ activation. Regulates insulin secretion through two different mechanisms: involved in glucose-induced insulin secretion downstream of insulin receptor in a pathway that involves AKT1 activation and TBC1D4/AS160 phosphorylation, and participates in the late step of insulin granule exocytosis probably in insulin granule fusion. Synthesizes PtdIns3P in response to insulin signaling. Functions in clathrin-coated endocytic vesicle formation and distribution. Regulates dynamin-independent endocytosis, probably by recruiting EEA1 to internalizing vesicles. In neurosecretory cells synthesizes PtdIns3P on large dense core vesicles. Participates in calcium induced contraction of vascular smooth muscle by regulating myosin light chain (MLC) phosphorylation through a mechanism involving Rho kinase-dependent phosphorylation of the MLCP-regulatory subunit MYPT1. May play a role in the EGF signaling cascade. May be involved in mitosis and UV-induced damage response. Required for maintenance of normal renal structure and function by supporting normal podocyte function. Involved in the regulation of ciliogenesis and trafficking of ciliary components.
Synonyms: PI3K-C2-alpha; PI3K-C2alpha; CPK; OCSKD; PI3-K-C2(ALPHA); PI3-K-C2A
Tractability: Small molecule: a structure with a bound ligand is known; a high-quality ligand is known; it has a binding pocket of medium quality; it belongs to a druggable protein family. Antibody: UniProt places it where antibodies can reach, with high confidence; its Gene Ontology location is reachable by antibodies, with high confidence. PROTAC: ubiquitination databases record sites on it; its protein half-life has been measured; a small molecule that binds it is known.
Target class: Enzyme; Transferase
Gene: Protein-coding gene on chromosome 11 (17,077,730 to 17,207,986, reverse strand). Ensembl gene ENSG00000011405.
Subcellular location: Cell membrane; Cytoplasmic vesicle, clathrin-coated vesicle; Nucleus; Cytoplasm; Golgi apparatus, trans-Golgi network
Subcellular location (Human Protein Atlas): Nucleoplasm; Cytosol; Vesicles
Pathways (Reactome):
Metabolism: Synthesis of PIPs at the Golgi membrane; Synthesis of PIPs at the early endosome membrane; Synthesis of PIPs at the late endosome membrane; Synthesis of PIPs at the plasma membrane
Vesicle-mediated transport: Clathrin-mediated endocytosis; Golgi Associated Vesicle Biogenesis
Gene Ontology:
Molecular function: 1-phosphatidylinositol-3-kinase activity; 1-phosphatidylinositol-4,5-bisphosphate 3-kinase activity; 1-phosphatidylinositol-4-phosphate 3-kinase activity; clathrin binding; kinase activity; phosphatidylinositol binding
Biological process: endocytosis; positive regulation of autophagy; positive regulation of cell migration involved in sprouting angiogenesis; cell migration; clathrin coat assembly; epidermal growth factor receptor signaling pathway; exocytosis; insulin receptor signaling pathway; membrane organization; phosphatidylinositol 3-kinase/protein kinase B signal transduction; phosphatidylinositol biosynthetic process; phosphatidylinositol-3-phosphate biosynthetic process; phosphatidylinositol-mediated signaling; platelet-derived growth factor receptor signaling pathway; vascular associated smooth muscle contraction; phosphatidylinositol phosphate biosynthetic process
Cellular component: clathrin-coated vesicle; cytoplasm; cytosol; extracellular exosome; membrane; nucleoplasm; nucleus; plasma membrane; trans-Golgi network; vesicle; Golgi apparatus
Genetic constraint (gnomAD): Loss-of-function variants: 31 observed, 66.01 expected, observed/expected ratio (o/e) 0.47, 90% interval 0.35 to 0.63. The upper end of that interval is the gene's LOEUF score, 0.63, which puts it in group 2 of 6, group 1 being the genes least tolerant of losing a copy. Missense variants: 752 observed, 883.06 expected, observed/expected ratio (o/e) 0.85, 90% interval 0.8 to 0.9. Synonymous variants: 295 observed, 312.76 expected, observed/expected ratio (o/e) 0.94, 90% interval 0.86 to 1.04.
Homologues: Orthologues: chimpanzee PIK3C2A (99% identical), macaque PIK3C2A (98% identical), dog PIK3C2A (94% identical), rabbit PIK3C2A (93% identical), pig PIK3C2A (92% identical), rat Pik3c2a (90% identical), mouse Pik3c2a (90% identical), guinea pig PIK3C2A (75% identical), tropical clawed frog pik3c2a (69% identical), zebrafish pik3c2a (61% identical), Drosophila melanogaster Pi3K68D (33% identical), Caenorhabditis elegans piki-1 (16% identical), and 2 more. Paralogues in human: PIK3C2B (45% identical), PIK3C2G (30% identical), PIK3CG (17% identical), PIK3CD (16% identical), PIK3CB (16% identical), PIK3CA (16% identical), PI4KA (14% identical), PIK3C3 (12% identical), PI4KB (9% identical).
Diseases named in the same sentence as PIK3C2A in open-access papers:
PIK3C2A is named in the same sentence as 64 diseases in open-access papers, as found by Europe PMC text mining. Sharing a sentence is not in itself a finding about the gene and the disease. The quoted sentences say what the papers report.
breast carcinoma (8 papers, 2019 to 2025). "In breast cancer models, PIK3C2A is required for genomic stability by regulating mitotic spindle formation." (PMID 34681622, 2021). "The reduction of PIK3C2A in breast cancer models initially impairs tumor growth but later leads to the convergent evolution of fast-growing clones with mitotic checkpoint defects." (PMID 34681622, 2021). "Interestingly, using standard IP-approach, we confirmed the interaction of FKBP4 with the catalytic subunit of PI3K, PIK3C2A, suggesting that the interaction between FKBP4 and PI3K could be central in the functional impact of FKBP4 in breast cancer cells." (PMID 31660083, 2019).
acute myocardial infarction (4 papers, 2019 to 2024). Necrosis of the myocardium, as a result of interruption of the blood supply to the area. "Instead, PIK3C2A gene might promote the occurrence of acute myocardial infarction by increasing the risk of thrombosis." (PMID 30946353, 2019). "This study aims to make an assessment on whether expression of PIK3C2A gene can be used as a biomarker for predicting the risk of acute myocardial infarction (AMI)." (PMID 30946353, 2019). "Meanwhile, the expression of PIK3C2A gene is irrelevant to the level of cardiac troponin I while the level of cardiac troponin can reflect the scope of myocardial infarction." (PMID 30946353, 2019). "As a result, we can reasonably infer that low expression of PIK3C2A gene may promote the occurrence of acute myocardial infarction through oxidative stress." (PMID 30946353, 2019). "We speculate that PIK3C2A may not predict the size of myocardial infarction." (PMID 30946353, 2019).
cataract (4 papers, 2019 to 2025). Partial or complete opacity of the crystalline lens of one or both eyes that decreases visual acuity and eventually results in blindness. "Mutations in PIK3C2A have been linked to a genetic syndrome characterized by dysmorphic features, short stature, skeletal abnormalities, and cataracts associated with ciliary dysfunction." (PMID 40045375, 2025). "We have applied these next-generation sequencing technologies to discover mutations in PIK3C2A that cause a newly identified genetic syndrome consisting of dysmorphic features, short stature, cataracts and skeletal abnormalities." (PMID 31034465, 2019). "Here we describe the identification of three independent families with homozygous loss-of-function mutations in PIK3C2A resulting in a novel syndrome consisting of short stature, cataracts, secondary glaucoma, and skeletal abnormalities among other features." (PMID 31034465, 2019). "Furthermore, homozygous loss-of-function mutations in PIK3C2A have been linked to developmental disorders characterized by short stature, craniofacial abnormalities, cataracts, skeletal defects, and neurological impairments." (PMID 40045375, 2025). "We identified homozygous loss-of-function mutations in PIK3C2A in children from three independent consanguineous families with short stature, coarse facial features, cataracts with secondary glaucoma, multiple skeletal abnormalities, neurological manifestations, among other findings." (PMID 31034465, 2019). "In addition to Lowe’s syndrome, there is partial overlap between PIK3C2A deficiency and yet other Mendelian disorders of PI metabolism such as the early-onset cataracts in patients with INPP5K deficiency, demonstrating the importance of PI metabolism in lens development." (PMID 31034465, 2019). "Recently, a novel human syndrome with short stature, cataracts, secondary glaucoma, and skeletal malformations has been identified in homozygous loss-of-function mutations in PIK3C2A (which encodes PI3K-C2α)." (PMID 36547473, 2022). "While PI3KC2α is essential in mice, human patients with inherited homozygous null mutations in the PIK3C2A gene display congenital syndromic features, including kidney failure and cataracts, due to early senescence of cells in the associated tissues." (PMID 36765741, 2023).
coronary artery disease (4 papers, 2018 to 2023). "Our results indicated that the level of PIK3C2A gene expression in peripheral blood of AMI patients was significantly lower than one in the non-coronary heart disease subjects." (PMID 30946353, 2019). "Additionally, a recent study showed decreased expression of EPC Pik3c2a in coronary artery disease reducing their angiogenic and vasculogenic abilities, which highlights its importance in blood vessels repair that is impaired in diabetes." (PMID 29995913, 2018).
diabetes (4 papers, 2018 to 2023). "Out of the 80 DE-genes, three genes Clcnka (downregulated) and Ptf1a and Pik3c2a (both up-regulated) are shared with the diabetes-associated genes list." (PMID 29995913, 2018). "Genes important for metabolic adaptation to diabetes include the transcription factor Clock, playing a role in PT gluconeogenesis and consequent serum glucose concentration in STZ-induced type 1 DM, Kdm1, an epigenetic regulator for salt-sensitive hypertension, and the kinases Pik3c2a, Pkn2." (PMID 37626062, 2023).
schizophrenia (4 papers, 2015 to 2019). A major psychotic disorder characterized by abnormalities in the perception or expression of reality. "Likewise, PIK3C2A identified in the gene-based analysis is located in a combined bipolar and schizophrenia GWAS locus." (PMID 28195573, 2017).
acute coronary syndrome (3 papers, 2023 to 2025). Signs and symptoms related to acute ischemia of the myocardium secondary to coronary artery disease. "PIK3C2A is a member of the phosphoinositide 3-kinase (PI3K) family and may be a risk factor for chronic stable angina and acute coronary syndrome (ACS)." (PMID 38020758, 2023). "PIK3C2A may contribute to the development of acute coronary syndrome (ACS) by affecting blood glucose levels and oxidative stress." (PMID 36830671, 2023).
ciliopathy (3 papers, 2019 to 2022). A genetic disorder of the cellular cilia or the cilia anchoring structures, the basal bodies, or of ciliary function. "Hallmark features of ciliopathies share many features with PIK3C2A deficiency and include skeletal abnormalities, progressive vision and hearing loss, mild to severe intellectual disabilities, polydactyly, and kidney phenotypes." (PMID 31034465, 2019). "Similar to the observation in mice models, patients’ fibroblasts exhibited decreased PtdIns3P and RAB11 levels at the ciliary base, as well as reduced cilia length, suggesting that PIK3C2A is a candidate ciliopathy gene." (PMID 36547473, 2022). "Similar to Pik3c2a-null cells, PIK3C2A mutant human fibroblasts exhibit reduced cilia length, suggesting that this PIK3C2A mutant syndrome may represent a new ciliopathy." (PMID 32970140, 2020). "Furthermore, heterozygous Pik3c2a deletion in several cystic kidney disease models exacerbates renal cyst formation, a typical ciliopathy phenotype." (PMID 32970140, 2020).
hepatocellular carcinoma (3 papers, 2015 to 2026). A malignant tumor that arises from hepatocytes. "PIK3C2A silencing reduces hepatoma cell proliferation and induces apoptotic cell death in a number of cancer cell lines." (PMID 26120366, 2015). "Here we reveal a ceRNA interaction between PIK3C2A and CD151 mRNAs in hepatocellular carcinoma (HCC) cells." (PMID 27270320, 2016).
gastrointestinal stromal tumor (2 papers, 2018 to 2022). "On the other hand, PIK3C2A expression is inhibited by miR-31 and miR-518A, leading to reduced cell proliferation and migration in osteosarcoma cells and gastrointestinal stromal tumors, respectively." (PMID 35269443, 2022). "As the last ncRNA in this subnetwork, miR-518a is down-regulated in imatinib-resistant gastrointestinal stromal tumor (GIST) and PIK3C2A was identified as the relevant specific target." (PMID 30211115, 2018).
Hypertension (2 papers, 2020 to 2025). The presence of chronic increased pressure in the systemic arterial system. "PIK3C2A was notably downregulated in CAD, particularly in ACS, compared to CSA, they discovered, while TXNIP was upregulated in STEMI-ACS patients who were non-diabetic smokers with hypertension and hypercholesterolemia." (PMID 41306139, 2025).
lung carcinoma (2 papers, 2018 to 2023). "Finally, Src-mediated MAPK signaling mitigates the anti-tumor activity of osimertinib in EGFR-TKI-sensitive lung cancer, and PIK3C2A mutations attenuate the effects of osimertinib in T790M-positive lung cancer." (PMID 29764505, 2018). "To explore the potential anti-tumor targets of apatinib, we have examined all tyrosine kinases and important silk/threonine kinases associated with lung cancer including Akt 1-3, FRAP1, PIK3C2A, PIK3C2B, BRAF, BRAF V600E and RAF1 in the Life platform." (PMID 36759818, 2023).
Bardet-Biedl syndrome (1 paper, 2019). A ciliopathy with multisystem involvement. "Many of these disorders, including Bardet-Biedl Syndrome, Meckel Syndrome, and Joubert Syndrome are also associated with decreased cilium length, as seen in PIK3C2A deficient cells." (PMID 31034465, 2019).
cholangiocarcinoma (1 paper, 2023). A carcinoma that arises from the intrahepatic biliary tree (intrahepatic cholangiocarcinoma) or from the junction, or adjacent to the junction, of the right and left hepatic ducts (hilar cholangiocarcinoma). "However, PIK3C2A expression was significantly increased in cholangiocarcinoma (CHOL), liver hepatocellular carcinoma (LIHC), and stomach adenocarcinoma (STAD)." (PMID 37063922, 2023).
colorectal cancer (1 paper, 2013). A primary or metastatic malignant neoplasm that affects the colon or rectum. "miR-30e* directly binds PIK3C2A 3ʹ UTR in colorectal cancer and IκBα 3ʹ UTR in glioma." (PMID 24312366, 2013).
congenital cataracts (1 paper, 2019). "In contrast, the phenotypes associated with Lowe’s syndrome share many of the same features with PIK3C2A deficiency including congenital cataracts, secondary glaucoma, kidney defects, skeletal abnormalities, developmental delay, and short stature." (PMID 31034465, 2019).
coronary artery stenosis (1 paper, 2019). "We believe that the expression of PIK3C2A gene cannot be used to predict the degree of coronary artery stenosis." (PMID 30946353, 2019).
endometriosis (1 paper, 2020). The growth of functional endometrial tissue in anatomic sites outside the uterine body. "FGFR2 and PIK3C2A have both previously been proposed to contribute to endometriosis-related carcinogenesis, but their role in benign endometriosis has not been elucidated." (PMID 33317189, 2020).
invasive breast carcinoma (1 paper, 2021). A carcinoma that infiltrates the breast parenchyma. "A subset of mutations found to be subclonal in the DCIS became dominant in the IDC‐NST, including a PIK3C2A missense mutation, suggesting that a minor subclone of the DCIS became the dominant clone in the progression from DCIS to invasive breast cancer." (PMID 33263939, 2021).
Kidney Cyst (1 paper, 2016). Abnormal fluid filled sac within the kidney, either acquired or congenital. "KO studies of the gene encoding PI3K-C2α (Pik3c2a) have implicated this isoform in angiogenesis, generation of the primary cilium and protection against kidney cyst formation." (PMID 27138914, 2016).
Lowe’s syndrome (1 paper, 2019). "The similarities between Lowe’s syndrome and PIK3C2A deficiency suggest that similar defects in phosphatidylinositol metabolism may underlie both disorders." (PMID 31034465, 2019). "The enzyme defective in Lowe’s syndrome, OCRL, is functionally similar to PIK3C2A as well, as it is also required for membrane trafficking and ciliogenesis." (PMID 31034465, 2019).
prostate carcinoma (1 paper, 2013). A carcinoma that arises from epithelial cells of the prostate gland. "The authors examined the association between several SNPs in PI3Ks genes (PIK3CD, PIK3C2A, PIK3R3, PIK3AP1, and PIK3C2B) and prostate cancer risk: among the five genes, only PIK3C2B showed a cluster of SNPs related to prostate cancer risk." (PMID 23658859, 2013).
renal clear cell carcinoma (1 paper, 2023). "The PIK3C2A expression in renal clear cell carcinoma (KIRC) was then validated utilizing Western blot." (PMID 37063922, 2023).
Salmonella Infections (1 paper, 2025). Infections with bacteria of the genus SALMONELLA. "The “Salmonella Infection” pathway includes HSP90AB1, IRAK4, and PIK3C2A, focusing on host-pathogen interactions and inflammation." (PMID 40621499, 2025).
Sepsis (1 paper, 2025). Sepsis is defined as life-threatening organ dysfunction caused by a dysregulated host response to infection. "Additionally, moderate colocalization evidence was observed for MAP2K5 (mitogen-activated protein kinase kinase 5), PIK3C2A (phosphatidylinositol-4-phosphate 3-kinase catalytic subunit type 2 alpha), and DSTYK (dual serine/threonine and tyrosine protein kinase) with sepsis outcomes (PPH4 > 0.5)." (PMID 40761792, 2025).
viral infection (1 paper, 2021). "We did identify 294 DML sites in CD4+ T lymphocytes that were associated with AHI at host genes such as EZR, MDM2, and PIK3C2A that play a role in viral activity suggesting that HIV-1 may be modifying CD4+ T lymphocytes DNA methylation states to promote viral infection and replication." (PMID 34388205, 2021).